ALLC (allantoicase)
Description:
The function of this enzyme is unclear as allantoicase activity is not known to exist in mammals.
Synonyms: ALC
Tractability: No criterion of Open Targets' tractability assessment is met for any kind of drug.
Gene: Protein-coding gene on chromosome 2 (3,658,200 to 3,702,671, forward strand). Ensembl gene ENSG00000151360.
Gene Ontology:
Molecular function: allantoicase activity
Biological process: allantoin catabolic process
Genetic constraint (gnomAD): Loss-of-function variants: 35 observed, 40.58 expected, observed/expected ratio (o/e) 0.86, 90% interval 0.66 to 1.14. The upper end of that interval is the gene's LOEUF score, 1.14, which puts it in group 5 of 6, group 1 being the genes least tolerant of losing a copy. Missense variants: 474 observed, 477.69 expected, observed/expected ratio (o/e) 0.99, 90% interval 0.92 to 1.07. Synonymous variants: 171 observed, 174.36 expected, observed/expected ratio (o/e) 0.98, 90% interval 0.87 to 1.11.
Homologues: Orthologues: chimpanzee ALLC (98% identical), macaque ALLC (96% identical), rabbit ALLC (87% identical), dog ALLC (84% identical), rat Dcdc2c (81% identical), mouse Allc (80% identical), guinea pig ALLC (74% identical), tropical clawed frog allc (54% identical), zebrafish allc (53% identical).
Diseases named in the same sentence as ALLC in open-access papers:
ALLC is named in the same sentence as 7 diseases in open-access papers, as found by Europe PMC text mining. Sharing a sentence is not in itself a finding about the gene and the disease. The quoted sentences say what the papers report.
asthma (2 papers, 2019 to 2024). "However, in vitro and/or in silico analyses provide additional evidence that genes discovered in these GWAS (e.g. GLCCI1, FBXL7, T gene, ALLC, CMTR1) might play a direct or indirect role in asthma/treatment response pathways." (PMID 30647901, 2019).
Alzheimer disease (1 paper, 2024). A progressive, neurodegenerative disease characterized by loss of function and death of nerve cells in several areas of the brain leading to loss of cognitive function such as memory and language. "We also observed 3 additional DMRs annotated to ZFP57, ALLC, ABI3, and all of them have been described to be involved in Alzheimer’s disease (AD)." (PMID 38845005, 2024).
gout (1 paper, 2016). A condition characterized by painful swelling of the joints, which is caused by deposition of urate crystals. "Analysis of the functional feature as defined by COGs revealed that the xanthine dehydrogenase (COG4360 and COG4361) was significantly enriched (P < 0.05, Wilcoxon rank-sum test) in gout patients, but the allantoicase (COG4266) depleted." (PMID 26852926, 2016).
kidney damage (1 paper, 2023). "CUBN-rs1801239 and DDR1-rs116772905 were associated with all the UACR-derived phenotypes, (along with SHROOM3-rs17319721 and ALLC-rs12615970, except for macroalbuminuria) at least in the overall and non-diabetic cohorts, but not with kidney damage." (PMID 37446387, 2023).
infection (2 papers, 2013 to 2021). The state of being infected such as from the introduction of a foreign agent such as serum, vaccine, antigenic substance or organism. "UO and ALLC expression was significantly increased in Plasmodium-infected mosquitoes 48 h post-infection when compared to mosquitoes fed on naïve blood, suggesting that ookinete invasion and/or the formation of early oocysts are responsible for these physiological changes." (PMID 35140633, 2021).
ALLC also shares sentences with these, for which no sentence is quoted: cryptococcosis (1 paper); deafness (1).